CXCL10 (C-X-C motif chemokine ligand 10)
Diseases named in the same sentence as CXCL10 in open-access papers (continued):
Sharing a sentence is not in itself a finding about the gene and the disease.
tumor (continued). "CXCL10 functions as a tumor- and inflammation-generating factor in a variety of pathological conditions." (PMID 39336734, 2024). "RT-qPCR and ELISA analyses were performed to measure the levels of IFN-β and CXCL10 in tumor tissues." (PMID 38685028, 2024). "The cytokines that exhibited a particularly strong positive correlation with tumor burden were CXCL10 (IP-10) (r = 0.8492, p = 0.0009) and CCL2 (r = 0.7851, p = 0.0042), also known as MCP-1." (PMID 39623404, 2024). "IFN-γ and CXCL10 are well characterized mediators of anti-tumor immune responses and have been identified as components of clinical signatures of response to PD-1 inhibition." (PMID 39697325, 2024). "Comparing changes in absolute cytokine levels for IFNγ and the IFNγ-inducible cytokines CXCL9 and CXCL10 to the tumor-related cytokines EGF, HGF and VEGF highlights the strong treatment related effects for IFNγ-pathway related cytokines." (PMID 38454126, 2024). "The CT26 supernatant also contains CXCL10, which has the potential to recruit T lymphocytes, transferring the “cold tumor” to the “hot tumor” characteristic." (PMID 38953994, 2024). "Increased levels of IRF1 in tumor cells in this study were associated with increased secretion of IFNγ by infiltrating NK and NKT cells and with induction of apoptosis by the CXCL10/CXCR3 paracrine axis." (PMID 38396830, 2024). "CXCL10 is also a chemokine that attracts and activates immune cells, participating in tumor development and prognosis." (PMID 39399504, 2024). "Activation of the IFN-α and IFN-β receptor subunit 1 IFNAR can lead to tumor-cell-mediated CXCL10 release." (PMID 39429695, 2024). "Quantitative PCR (qPCR) analysis indicates a significant increase in mRNA expression levels of both Ifng and Cxcl10 in P815-IFNG cells compared to the P815-M cells (control tumor group)." (PMID 39080467, 2024). "Through binding to its unique receptor, CXC chemokine receptor 3 (CXCR3), CXCL10 exhibits pleiotropic functions in tumor biology." (PMID 38720149, 2024). "Compared to CARD, the SDePER recovered the cell-type proportion at a higher resolution and imputed CXCL10 expression remarkedly better resembled the lymphoid tissue 2 on the periphery of the tumor." (PMID 39402626, 2024). "In general, the specific kinds of receptors and cells involved appear to be the determining factors in the contradictory effects of CXCL10 on tumor growth." (PMID 39273452, 2024). "The release of CCL5 and CXCL10 is essential for recruiting cytotoxic immune cells into the tumor microenvironment and enhancing the efficacy of cancer immunotherapy." (PMID 40395527, 2024). "For instance, CCR4/5 and CXCR3, expressed by CD8+ T cells, allow their ligands CCL5, CXCL9, and CXCL10 to guide the migration of CD8+ T cells into tumor tissue." (PMID 39769501, 2024). "Following dual PD-1/CTLA-4 blockade, macrophages secrete CXCL9 and CXCL10, increasing tumor infiltration of CD8+ T cells." (PMID 39114657, 2024). "In the invasive margin of CRC liver metastasis (CRC-L), CCL5+CD4 and CD8 cells, recruited by myeloid-derived CXCL9 and CXCL10, attract macrophages promoting invasion and tumor growth by MMP." (PMID 39100682, 2024). "For example, CCL5 produced by tumor cells or CXCL9 and CXCL10 also expressed by tumor-resident myeloid cells determine effector T-cell recruitment to the tumor microenvironment." (PMID 39669575, 2024). "Mammary epithelial cells lacking USP18 induce the recruitment of Th1-subtype CD4 T cells by increasing IFN-γ-mediated Cxcl10 secretion, thus forming a tumor-suppressive microenvironment." (PMID 39334957, 2024). "Consistent with accumulation of nAlb at tumor sites, we found a notable increase in the expression of genes associated with STING pathway activation, including Ifnb1, Cxcl10, Cxcl9, and Tnfa." (PMID 38766114, 2024).
tumor (continued). "In conclusion, systemic administration of either CXCL9-Fc or CXCL10-Fc markedly increases the relative number of activated highly potent tumor-specific CD8+ T cells at the tumor site, and to some extent PD-1 expression on about 7-10% of these cells." (PMID 39474427, 2024). "Together, these findings support the idea that APG-2575 has an important effect on enhancing CCL5- and CXCL10-mediated CD8+ T-cell recruitment into the TME to promote tumor regression." (PMID 38062129, 2024). "In mice receiving only carbo/pax chemotherapy, strong positive correlations with tumor burden were found for IL-7 (r = 0.8734, p = 0.0230), IL-10 (r = 0.8912, p = 0.0171), and CXCL10 (IP-10) (r = 0.9433, p = 0.0047)." (PMID 39623404, 2024). "The results revealed that Mn‐N/C plus H2O2 treatment notably stimulated high expression levels of IFNα, IFNβ, and ISGs including Irf7, Isg15, and Cxcl10 in MC38 tumor cells." (PMID 38308189, 2024). "Conversely, tumor-derived CXCL10 can interact with CXCR3 to induce tumor cell proliferation, angiogenesis, and other pro-tumorigenic effects." (PMID 38720149, 2024). "The CXCL9 and CXCL10/CXCR3 axes play two roles in the tumor environment: paracrine signaling for immune activation and autocrine signaling for cancer proliferation and metastasis." (PMID 38720340, 2024). "The expression of CXCL10 is elevated in tumor tissue compared to normal bladder tissue, specifically in high-grade, non-papillary tumors." (PMID 39409924, 2024). "Overall, our study provides compelling evidence for the pivotal role of tumor-intrinsic IFNα and CXCL10 in orchestrating the immunotherapeutic response within the tumor microenvironment." (PMID 38953994, 2024). "First among these were CXCL9 and CXCL10, both of which have been linked to enhanced CAR T cell anti-tumor activity." (PMID 39566469, 2024). "The CXCR3/CXCL10 axis has been known for its pro-metastatic potential and is highly expressed in several tumour types." (PMID 39146303, 2024). "A previous study examining the impact of specific DPP4 inhibition in murine cancer models has demonstrated that DPP4 inhibition not only elevates tumor CXCL10 levels but also enhances the trafficking of CXCR3+ NK cells and CD8+ T cells into tumors." (PMID 38672409, 2024). "On the contrary, the recruitment of CXCR3-expressing T cells has been associated with an improved antitumor immunity, and IFNG and CXCL10 have been shown to inhibit the growth of MM cells, pointing towards a potential role in immune-mediated tumor control." (PMID 39613747, 2024). "Prior investigations have revealed that CXCL10 exhibits both tumor-promoting and tumor-suppressing effects." (PMID 38225277, 2024). "IT CXCL9-DC or CXCL10-DC provided similar efficacy as compared to CXCL9/10-DC in the KPL-3M tumor-bearing mice." (PMID 38518770, 2024). "The findings suggest that IFNs-mediated CXCL10 expression, along with PD-L1, plays a significant role in modulating the immune response within the tumor microenvironment." (PMID 38953994, 2024). "Blocking CXCL10 with AMG487 has the potential to reverse the pro-tumor effect and enhance immunotherapeutic efficacy when combined with anti-PD-L1 antibody." (PMID 39524442, 2024). "ALKBH5 was found to recruit programmed death-ligand 1-positive tumor-associated macrophages and promote M2 macrophage polarization by inducing the secretion of CCL2 and CXCL10." (PMID 38872221, 2024). "Subsequent scRNA-seq data analysis indicated that patients with higher presence of CXCL10+ M1 macrophages in tumor tissues are more likely to benefit from neoadjuvant therapy." (PMID 39170612, 2024). "The CXCR3-CXCL9/CXCL10 chemokine axis, mobilized by Th1 cells, can also participate in antitumor responses remodeling tumor immunity through the production of interferon gamma (IFN-γ)." (PMID 39769501, 2024). "It has been shown to activate the transcription of several genes such as CXCL10, as well as modulate immune response and tumor development." (PMID 39724092, 2024).
tumor (continued). "Differently, CXCL10 can recruit natural killer (NK) cells, cytotoxic T lymphocytes, and macrophages, playing a crucial role in anti-tumor immunity through CXCL9/10/11-CXCR3 axes." (PMID 38475811, 2024). "The blood levels of cytokines such as IL-2 (P = 0.0391) and CXCL10 (P = 0.0195) were also significantly increased in the pCR group, which is consistent with the high density of activated cytotoxic T cells at the tumor site (P < 0.0001)." (PMID 38619623, 2024). "Compared with the control treatment, CCL5 and CXCL10 blockade abrogated the effect of APG-2575 on tumor growth." (PMID 38062129, 2024). "We implemented in situ hybridization to detect messenger ribonucleic acid (mRNA) transcripts of CXCL9, CXCL10, and IL-8 along with a synaptophysin immunohistochemical co-stain to identify tumor cells." (PMID 38822345, 2024). "Consistent with cytokine profiling, real-time PCR data confirmed upregulation in the expression of IL8, Cxcl10, Il1β, and Ccl2 in tumor lysates." (PMID 39768223, 2024). "As previously acknowledged, CCL5 and CXCL10 as pivotal signaling bridges between NK cells and T cells, and tumor cells." (PMID 38550593, 2024). "Considering that long-term exposure to IFNG alters tumor phenotypes and a dose-dependent effect of IFNG in tumor microenvironment, the Ifng-Cxcl10 loop needs to be precisely regulated to avoid producing side effects." (PMID 39080467, 2024). "RT-qPCR was employed to detect the mRNA levels of these chemokines in tumor tissues of our exercise models, confirming that Ccl5, Cxcl10, Cxcl9, and Cxcl11 were significantly increased in Ex mice compared to the Ctrl group." (PMID 38622609, 2024). "One of the resultant effects is an increased expression of the chemokines CCL5 and CXCL10, resulting in T-cell recruitment and an enhancement of lymphocyte function in the tumour." (PMID 39796639, 2024). "IRF1 increased CXCL10 gene transcription and exhibited antiproliferative and pro-apoptotic effects on tumor cells, presumably by activating the CXCL10/CXCR3 autocrine pathway." (PMID 38396830, 2024). "Previous data suggest that once pIRF3 enters the nucleus, it activates the type I IFN response, consequently stimulating the secretion of chemokines, Chemokine (C-C motif) ligand 5 (CCL5), and C-X-C Motif Chemokine Ligand 1 (CXCL10) in tumor cells." (PMID 38169513, 2024). "Cytokines CXCL9 and CXCL10, when released from tumor cells following irradiation, can drive T cell chemotaxis, facilitating their migration into the tumor microenvironment." (PMID 38323315, 2024). "CXCL10, a chemokine known to negatively regulate recruitment of anti-tumor immune cells to tumor microenvironment (TME), was elevated post-treatment in patients with NCB, but not in patients with CB." (PMID 38236249, 2024). "The application of IFNγ neutralizing antibodies, knockdown of CXCL9/CXCL10 gene, or CXCR3 blockade of macrophages all cause the attenuation of anti-tumor immune response." (PMID 38787372, 2024). "HLA-DRA also showed a surprising positive correlation with CCL4, CCL5, CXCL9, and CXCL10, indicating its beneficial role in the human immune response through inducing immune cell infiltration and improving tumor clearance in the body." (PMID 38931345, 2024). "In a murine PDAC model, we found that intrinsic loss of SIN3B within tumor cells enhances CD8+ T cell infiltration by increasing the secretion of IFNγ‐induced chemokines CXCL9 and CXCL10." (PMID 39316363, 2024). "At the whole tumor level, there was also a 2.3-fold increase in the expression of CXCL10 in MH-treated mice (p = 0.0131)." (PMID 38444857, 2024). "Based on these findings, we designed a light-controlled Infg-Cxcl10 gene loop to manipulate the tumor microenvironment." (PMID 39080467, 2024). "Compared to LL/2, we found that CT26 exhibited higher IFNs and CXCL10 levels in this study, which potentially further increased T lymphocyte recruitment in tumor microenvironment." (PMID 38953994, 2024).
tumor (continued). "In the first set of experiments, a relatively low dose (50μg/mouse) of CXCL9-Fc or CXCL10-Fc was administered, starting 3 days after tumor engraftment." (PMID 39474427, 2024). "Collectively these results further highlight the role of CXCL9 and CXCL10 in potentiating, not only anti-tumor CD8+ T cells but also anti-tumor CD4+ T cells, including cytotoxic CD4+ T cells." (PMID 39474427, 2024). "Like CXCL9, CXCL10 and CXCL11 expression, HLA-DR expression on tumor cells is tightly linked to IFN-γ signaling." (PMID 38822345, 2024). "The authors suggest that LPS-mediated TLR4 activation of mast cells induced the release of CXCL10, a chemokine that attracts effector T cells to tumor." (PMID 39126091, 2024). "For instance, autophagy enhances the secretion of CXCL10, a chemokine that attracts effector T cells and NK cells to the tumor site, thereby strengthening the immune response." (PMID 39840028, 2024). "In this context, we established that calycosin, a bioactive compound extracted from Radix astragali, exerts its anti-tumor function by downregulating CXCL10 expression in GBM." (PMID 38461458, 2024). "The production of CXCL10 by migratory CD8+ T cells in response to local IFN-I within the tumor microenvironment (TME) allows for the migration of effector T cells into the tumor." (PMID 38672681, 2024). "A different model of NSCLC-bearing mice also showed reduced tumor growth when the mice were injected with human recombinant CXCL10." (PMID 38928238, 2024). "Key chemokines including CXCL9 and CXCL10 have been shown to attract CD8+ cytotoxic T cells to the tumor microenvironment." (PMID 38822345, 2024). "The comparison between LL/2 and CT26 cell lines, representing immunotherapy-resistant and immunotherapy-sensitive tumors, respectively, further supports the roles of IFNα and CXCL10 in mediating anti-tumor immunity." (PMID 38953994, 2024). "For example, CXCR3, when expressed by CD8+ T cells, allows their ligands CXCL9 and CXCL10 to guide the migration of CD8+ T cells to tumor tissue, resulting in an anti-tumor effect." (PMID 39769501, 2024). "The CXCL9/CXCL10/CXCR3 axis plays a role in recruiting tumor-infiltrating lymphocytes (TILs) to tumors across various cancers, indicating a potential anti-tumor function." (PMID 39409924, 2024). "PepO-primed M2 macrophages decreased the expression of tumor-supportive molecules like Arg-1, Tgfb, Vegfa and IL-10, and increased the expression of iNOS, Cxcl9, Cxcl10, TNF-α and IL-6 to inhibit TNBC growth." (PMID 37925462, 2023). "As well, in vivo studies would be important to determine any significant impact on the tumor from the biological activity of the increased production of IFNβ and CXCL10 levels elicited by the rHDL-DPM-DMXAA NPs compared to the Free DMXAA." (PMID 40838054, 2023). "Mechanistically, LDRT sensitizes tumors to DPVB by recruiting stem-like CD8+ Tpex, the progenitor exhausted CD8+ T cells, from draining lymph nodes (dLNs) into the tumor via the CXCL10/CXCR3 axis." (PMID 38001101, 2023). "CCL5, CCL-11, CXCL9, and CXCL10 are postulated as the main drivers in eosinophil-mediated tumor cell necrosis." (PMID 36427017, 2023). "CXCL9 and CXCL10 can be generated by antigen-presenting cells (dendritic cells and macrophages) and by tumor cells." (PMID 37063837, 2023). "We did not observe changes in T-cell infiltration in our MC38 tumor model, which is a tumor with higher immune cell infiltration and has high basal levels of cytokines, including CXCL10." (PMID 37478172, 2023). "Genetic engineering-attenuated bacterial OMVs derived from E. coli (∆msbB) were specifically targeted and accumulated in the tumor field while inducing the expression levels of antitumor cytokines CXCL10 and INF-γ eventually led to tumor regression." (PMID 37896250, 2023). "CXCL10, a known chemoattractant that exhibits anti‐tumour activity, was particularly prominent, with its expression up‐regulated in the co‐cultures with either NPFs or CAFs by up to three orders of magnitude." (PMID 36608258, 2023).
tumor (continued). "On the other hand, it has also been demonstrated that tumor-cell-derived CXCL9/CXCL10 regulates the recruitment of T cells in various tumors." (PMID 37109526, 2023). "In turn, the IL9-polarized macrophages secreted chemokines, including CCL3, CCL4, CXCL9, and CXCL10, to recruit antitumor T cells, NKs, DCs, and macrophages to infiltrate the tumor." (PMID 36968220, 2023). "In our studies, tumor-localized CXCL10 induction was correlated with higher frequency of CD8+ T cells within tumors." (PMID 36949064, 2023). "CCL19, CXCL10, and CXCL13 transcript expression levels were significantly associated with tumor stage (lowest levels in stage 2) in the TCGA-SKCM cohort." (PMID 37435077, 2023). "This study showed that neutrophils involved in their anti-tumor activity involve a cell subpopulation with upregulated CXCL10 and MHC-II expression levels." (PMID 38002062, 2023). "On the contrary, M1 TAMs produce proinflammatory cytokines, such as TNF and IL-12; recruit Th1 CD4+ T cells through CXCL9 and CXCL10 secretion; and induce direct tumor cell killing." (PMID 37377970, 2023). "ILC3 secretes chemokine CXCL10 inside the tumor, which encourages antitumor immune responses by recruiting CD4+ and CD8+ T cells." (PMID 37937304, 2023). "Due to down-regulation of CXCL10 expression level, the migration of NK cells at tumor sites was decreased and NK-cell-mediated tumor growth inhibition was attenuated." (PMID 37268997, 2023). "The results showed that high IERS was associated with high tumor purity, high activated CD4 memory cells, M0 and M1 macrophage abundance, high PD-L1, CXCL10, and GZMB expression." (PMID 36936970, 2023). "IFN-γ has strong antitumor functions that also rely on the induction of an anti-angiogenic cascade involving MIG and IP10 (CXCL9 and CXCL10) and on a direct inhibitory effect on tumor cell growth in vivo." (PMID 36934257, 2023). "Accordingly, in hepatic cancer, the inhibition of EZH2 in tumor cells enhanced NK recruitment via CXCL10, and it enhanced their activation through the expression of NKG2D ligands." (PMID 36900330, 2023). "In the future, the ability to evaluate anti-tumor neutrophils and MDSCs using common molecules, such as CXCL10 and MHC-II, in humans and mice will pave the way for the development of immunotherapy using mouse models." (PMID 38002062, 2023). "The increase in circulating IP-10 and MIG is consistent with the observed increase in RNA expression of their encoding genes CXCL10 and CXCL9 in tumor samples." (PMID 37507657, 2023). "Olaparib and atezolimumab (anti-PD-L1) increased IFNγ, TNFα, and CXCL9/CXCL10 expression and tumor infiltration by lymphocytes." (PMID 36831435, 2023). "In cutaneous melanoma mouse models, temozolomide increased the expression of CCL5, CXCL9, and CXCL10, resulting in increased T-cell trafficking to the tumor." (PMID 36949946, 2023). "For instance, a study showed that IL‐18 and CXCL10 are correlated with the degree of tumor response in 32 NSCLC patients who received PD‐1/PD‐L1 inhibitors." (PMID 37062076, 2023). "But treatment with the modulators combined with anti-PD1 antibody strikingly increases CXCL9 and CXCL10 expression in DCs, resulting in a significant delayed tumor growth and prolonged mouse survival." (PMID 37928272, 2023). "These genes included those related to P/DAMP signaling (e.g., Il6, Tlr1, Tlr4, Il1b, Il18), necroptotic tumor cell death (e.g., Casp1, Casp8, Il1b), and activation of the adaptive immune system (e.g., Cd80, Cd8a, Ccr5, Cxcl10)." (PMID 37213298, 2023). "Mechanistically, MFAP5 deficiency in CAFs downregulates HAS2 and CXCL10 via MFAP5/RCN2/ERK/STAT1 axis, leading to angiogenesis, hyaluronic acid (HA) and collagens deposition reduction, cytotoxic T cells infiltration, and tumor cells apoptosis." (PMID 37156839, 2023). "As previous study has demonstrated, CXCL10 is primarily produced by antigen-presenting cells (APCs), including dendritic cells and macrophages, as well as tumor cells." (PMID 38001101, 2023).